BNC2 (basonuclin zinc finger protein 2)
Description:
Probable transcription factor specific for skin keratinocytes. May play a role in the differentiation of spermatozoa and oocytes. May also play an important role in early urinary-tract development.
Synonyms: BSN2; FLJ20043; bn2; LUTO
Tractability: PROTAC: UniProt records ubiquitination sites on it.
Gene: Protein-coding gene on chromosome 9 (16,409,503 to 16,870,902, reverse strand). Ensembl gene ENSG00000173068.
Subcellular location: Nucleus
Subcellular location (Human Protein Atlas): Nucleoli fibrillar center; Nuclear bodies
Gene Ontology:
Molecular function: protein binding
Biological process: regulation of DNA-templated transcription
Cellular component: fibrillar center; nuclear body; nucleus
Genetic constraint (gnomAD): Loss-of-function variants: 20 observed, 79.72 expected, observed/expected ratio (o/e) 0.25, 90% interval 0.18 to 0.37. The upper end of that interval is the gene's LOEUF score, 0.37, which puts it in group 1 of 6, group 1 being the genes least tolerant of losing a copy. Missense variants: 1,382 observed, 1,470.9 expected, observed/expected ratio (o/e) 0.94, 90% interval 0.9 to 0.98. Synonymous variants: 582 observed, 541.28 expected, observed/expected ratio (o/e) 1.08, 90% interval 1 to 1.15.
Homologues: Orthologues: chimpanzee BNC2 (99% identical), rabbit BNC2 (98% identical), guinea pig BNC2 (97% identical), mouse Bnc2 (97% identical), macaque BNC2 (97% identical), rat Bnc2 (97% identical), dog BNC2 (95% identical), pig BNC2 (94% identical), tropical clawed frog bnc2 (77% identical), zebrafish bnc2 (66% identical), Drosophila melanogaster disco-r (17% identical), Drosophila melanogaster disco (10% identical), and 1 more. Paralogues in human: BNC1 (40% identical).
Diseases named in the same sentence as BNC2 in open-access papers:
BNC2 is named in the same sentence as 68 diseases in open-access papers, as found by Europe PMC text mining. Sharing a sentence is not in itself a finding about the gene and the disease. The quoted sentences say what the papers report.
ovarian carcinoma (7 papers, 2012 to 2025). A malignant neoplasm originating from the surface ovarian epithelium. "Coupled with observations that BNC2 expression is lower in ovarian cancer cell lines compared with normal tissue and that the deletion of SNP-containing regions decreases expression, BNC2 was thereby implicated as an important cancer-associated gene." (PMID 37536977, 2023). "Single-nucleotide polymorphisms (SNPs) in the physical proximity of the BNC2 gene were identified by genome-wide association study (GWAS) as having the highest association with ovarian cancer risk." (PMID 37536977, 2023). "Although having less than five publications indicating associations, BNC2 has also been associated with ovarian cancer in two GWAS, both reaching genome wide significance." (PMID 27042214, 2016). "Rs786100 is an intronic SNP in BNC2 gene at chromosome 9, BNC2 gene is associated with ovarian cancer." (PMID 26536629, 2015). "Indeed, zebrafish bnc2 mutant females are infertile and human BNC2 variants are associated with ovarian cancer predisposition; potential defects in other systems have yet to be ascertained." (PMID 23737760, 2013). "In one of the most recent genome-wide association study (GWAS) conducted in ovarian cancer, a strong association with 12 single-nucleotide polymorphisms (SNPs) in the Basonuclin 2 (BNC2) gene was found, where the minor allele of the associated SNPs were protective against disease." (PMID 23095717, 2012). "Recent findings demonstrated that circ-BNC2 inhibits ovarian cancer progression via the miR-223-3p/FBXW7 axis." (PMID 40963633, 2025). "In ovarian cancer, FBXW7 expression is reduced and inversely associated with miR-223-3p while positively correlating with circ-BNC2, and it functionally suppresses invasion and migration." (PMID 40963633, 2025). "This work focuses on the function and molecular mechanism of circRNA-BNC2 (circ-BNC2) (also known as hsa_circ_0008732) in ovarian cancer (OC)." (PMID 35965327, 2022). "Seemingly in contradiction, however, BNC2 has been proposed to act as a likely tumour suppressor as it exhibits lower expression in ovarian cancer cell lines than in non-cancerous ovarian cells." (PMID 37536977, 2023).
hypospadias (5 papers, 2019 to 2023). Hypospadias is the displacement of the urethral meatus on the ventrum of the penis. "In patient 5, six variants in six genes were found: BNC2, FGF10, HSD3B2, IRX5, MAML2 and NOTCH2; all, except MAML2, have also been associated with hypospadias or gonadal development." (PMID 31555317, 2019).
scoliosis (4 papers, 2016 to 2019). A congenital or acquired spinal deformity characterized by lateral curvature of the spine. "GPR126 knockdown and BNC2 overexpression in zebrafish have been shown to cause delayed ossification of the developing spine and scoliosis." (PMID 29145830, 2017). "Actually, the over-expression of Bnc2 in zebrafish caused scoliosis-like deformity." (PMID 29549362, 2018). "GPR126 and BNC2 were reportedly two of the candidate susceptibility genes for AIS, and GPR126 knockdown or BNC2 overexpression in zebrafish has been shown to cause delayed ossification of the developing spine and scoliosis." (PMID 27733146, 2016).
breast carcinoma (3 papers, 2016 to 2023). "BNC2, a TF previously associated with a mesenchymal breast cancer stem cell phenotype, is particularly strongly mesenchymal specific, and is consistently responsive to miR-200c perturbation across cell lines." (PMID 31372646, 2019). "In an effort to characterize such tumours, individual breast cancer patient biopsies were scored against an E/M gene expression signature, which indicated that tumours with high BNC2 expression are more mesenchymal in their nature." (PMID 37536977, 2023). "In this study, we sought to explore the role of BNC2 in mesenchymal breast cancer cells in which it is naturally highly expressed." (PMID 37536977, 2023). "We also find BNC2 is down-regulated in 9 of 28 cancer types, including breast cancer, and trends toward down-regulation in a further seven, whereas up-regulation is observed in six cancer types, only three of which being statistically significant." (PMID 37536977, 2023). "GWAS that implicate BNC2-associated alleles with adolescent idiopathic scoliosis also implicate other ECM-associated genes and cytokines that we also find to be under BNC2 control in our breast cancer system (MATN1, MMP9, SOX9, IL-6 as examples)." (PMID 37536977, 2023). "As we do not possess an antibody that unequivocally detects endogenous BNC2, we examined single-cell sequencing derived from 26 breast cancer patients (>130 K single cells) to determine cell-specific BNC2 expression." (PMID 37536977, 2023). "BT549 and HS578T breast cancer cells were selected for previous experiments, specifically because of their high expression of BNC2." (PMID 37536977, 2023). "We find that at endogenous levels, BNC2 controls the expression of specific collagens, matrix metalloproteases, and other matrisomal components in breast cancer cells, and in fibroblasts that are primarily responsible for the production and processing of the ECM within the tumour microenvironment." (PMID 37536977, 2023). "In contrast, however, reference 51 reports BNC2 knockdown decreased collagen expression in hepatic stellate cells, whereas we find in mammary fibroblasts (and BNC2-expressing breast cancer cells), BNC2 knockdown increases the expression of collagen (both mRNA and secreted collagen protein)." (PMID 37536977, 2023). "Similarly, to breast cancer cells, BNC2 knockdown in mammary fibroblasts strongly down-regulates the expression of select MMPs and up-regulates the expression of specific collagens at both the RNA and protein levels." (PMID 37536977, 2023). "EOC and breast cancer share some common risk factors (e.g. BRCA1/2 status); therefore, it might be expected that BNC2 has a role also in breast cancer onset." (PMID 27899818, 2016). "Furthermore, MDA-MB-231 mammary tumour cells seeded into the CDM derived from fibroblasts in which BNC2 had been knocked down exhibited a trend towards reduced motility relative to those seeded into CDM derived from fibroblasts that had been transfected with control non-targeting siRNA." (PMID 37536977, 2023). "Accordingly, BNC2 expression is positively correlated with these genes and with other markers of mesenchymal cells across cancer cell line encyclopedia (CCLE) and breast cancer patients (TCGA)." (PMID 37536977, 2023).
liver fibrosis (3 papers, 2022 to 2023). "The CDAA-HFSC diet was used since it triggers induction of Bnc2 expression concomitant with moderate NASH-associated liver fibrosis." (PMID 36088459, 2022). "This study, together with a recent publication detailing the involvement of BNC2 in myofibroblasts during liver fibrosis, directly implicates BNC2 as a regulator of the ECM." (PMID 37536977, 2023). "A multi-omics analysis has evidenced the crucial role of the transcription factor Basonuclin 2 (BNC2) in the activation of canonical pathways driving myofibroblastic activation in the context of liver fibrosis." (PMID 38124183, 2023). "The authors found that BNC2 transcriptional induction is a specific feature of in vivo myofibroblastic activation in liver fibrosis, extended to lung or heart injury, indicating BNC2 as a marker of myofibroflasts across different organs." (PMID 38124183, 2023). "Altogether, these data indicated that induction of BNC2 expression is an intrinsic feature of myofibroblastic activation which characterizes mouse and human liver fibrosis." (PMID 36088459, 2022). "Using liver fibrosis as a model for in-depth investigations, we first show that BNC2 expression is induced in both mouse and human fibrotic livers from different etiologies and decreases upon human liver fibrosis regression." (PMID 36088459, 2022). "Here, the authors report that the transcription factor Basonuclin 2 (BNC2) integrates fibrogenic signals and drives myofibroblastic transcriptional activation in liver fibrosis." (PMID 36088459, 2022). "We found that Bnc2 expression was increased in mouse fibrotic livers obtained through repeated injection of carbon tetrachloride (CCl4) for 8 weeks, a classical model of hepatotoxicity-induced liver fibrosis." (PMID 36088459, 2022). "Interestingly, liver fibrosis regression obtained through bariatric surgery was accompanied by reduced BNC2 expression levels as demonstrated by RNAscope assays in four patients." (PMID 36088459, 2022). "Hence, Bnc2 expression was consistently induced in different mouse liver fibrosis models." (PMID 36088459, 2022).
serous ovarian carcinoma (3 papers, 2016 to 2024). "The BNC2 level was reduced in high-grade serous ovarian cancer samples compared to that in control samples, and the reduction in BNC2 levels increased cell survival after H2O2 treatment." (PMID 38540700, 2024). "The deletion of the BNC2 gene and the corresponding decreased expression of BNC2 mRNA have been detected in Barrett’s esophagus, hepatocellular carcinoma and high-grade serous ovarian carcinoma." (PMID 28184177, 2017). "Rs3814113 is the single-nucleotide polymorphism (SNP) showing the strongest association with high-grade serous ovarian carcinoma (HGSOC) incidence and is located in an intergenic region about 44 kb downstream of basonuclin 2 (BNC2) gene." (PMID 27899818, 2016).
skin cancer (3 papers, 2018 to 2025). "This SNP is located in an enhancer region that regulates BNC2 transcription in melanocytes, suggesting a potential link between BNC2 and skin cancer-related phenotypes." (PMID 39923055, 2025). "Three studies identified an association between the intergenic region between BNC2 and ENSG00000237153 (OR = 0.907, CI = 0.894–0.920) and skin ageing phenotypes specifically related to skin cancer, including basal cell carcinoma and cutaneous squamous cell carcinoma." (PMID 39923055, 2025). "BNC2, HERC2, OCA2, RALY, and TYR are pleiotropic for Category B Phenotypes (skin colour phenotypes) and Category C Phenotypes (skin cancer phenotypes)." (PMID 35907981, 2022).
adolescent idiopathic scoliosis (2 papers, 2022 to 2023). A scoliosis with no known cause arising in adolescent. "In humans, BNC2 mutations have been linked to congenital lower urinary-tract obstruction, adolescent idiopathic scoliosis, and ovarian cancer." (PMID 36088459, 2022).
Barrett esophagus (2 papers, 2016 to 2017). Esophageal lesion lined with columnar metaplastic epithelium which is flat or villiform. "Akagi and colleagues detected the decreased expression of BNC2 mRNA in esophageal adenocarcinoma cells and showed that the stable expression of BNC2 caused the growth arrest of tumor cells, which suggests that BNC2 is a tumor suppressor." (PMID 28184177, 2017). "In esophageal adenocarcinoma cells, the stable expression of BNC2 caused the growth arrest of tumor cells, suggesting that BNC2 might also be a tumor suppressor gene." (PMID 28184177, 2017). "In esophageal adenocarcinoma cells, stable expression of BNC2 caused the growth arrest of tumor cells, suggesting that BNC2 might also be a tumor suppressor gene." (PMID 26821013, 2016). "Moreover, deletion of the BNC2 gene and decreased expression of BNC2 mRNA have been detected in Barrett’s esophagus tumor tissues." (PMID 26821013, 2016).
depression (2 papers, 2023 to 2024). "Here, we explored the function of circ‐Bnc2 in LPS‐induced microglial cell neuroinflammation and neuron cell apoptosis to reveal its role in depression progression." (PMID 36960892, 2023). "Here, the role of circ‐Bnc2 in LPS‐stimulated microglia cells neuroinflammation and neuron cells apoptosis was explored to confirm its function in depression progression." (PMID 36960892, 2023). "Through the hypothesis of circRNA/miRNA/mRNA axis, we further revealed the potential molecular mechanism of circ‐Bnc2 in regulating depression progression." (PMID 36960892, 2023). "Circ‐Bnc2 has been shown to be significantly downregulated in depression mice, but its role in the progression of depression remains unclear." (PMID 36960892, 2023). "In summary, our results confirmed that circ‐Bnc2 could inhibit neuroinflammation and neuron cell apoptosis by regulating miR‐497a‐5p/HECTD1 axis, suggesting that circ‐Bnc2 might be a potential target for depression treatment." (PMID 36960892, 2023). "In the rescue experiments, the inhibition effect of circ‐Bnc2 on neuroinflammation in microglia cells and apoptosis in neuron cells could be reversed by overexpressing miR‐497a‐5p, confirming that circ‐Bnc2 targeted miR‐497a‐5p to alleviate depression progression." (PMID 36960892, 2023). "Therefore, circ‐Bnc2 might be a vital circRNA regulating depression progression." (PMID 36960892, 2023). "In addition, rs263575 [BNC2/CNTLN] had a marginally significant indirect effect on broad depression among females but not males, and rs2402273 [LSM8/CTTNBP2] had a marginally significant indirect effect on broad depression among males but not females." (PMID 38790194, 2024). "In a previous study, mmu_circ_0001223 (derived from Bnc2 gene, also called circ‐Bnc2) was found to be significantly downregulated in a chronic unpredictable mild stress mice model, and its overexpression could promote the protein expression of CREB1 and BDNF to alleviate depression progression." (PMID 36960892, 2023).
hepatocellular carcinoma (2 papers, 2016 to 2017). A malignant tumor that arises from hepatocytes. "Here, we investigated the expression and methylation status of two Basonuclin homologs, BNC1 and BNC2 in hepatocellular carcinoma (HCC)." (PMID 26821013, 2016).
melanoma (2 papers, 2016 to 2026). A malignant, usually aggressive tumor composed of atypical, neoplastic melanocytes. "We also identified BNC2 as a strong risk-insertion binding protein to the risk-associated allele of rs59308963 in melanoma cells." (PMID 41542517, 2026).
Obesity (2 papers, 2024 to 2026). Accumulation of substantial excess body fat. "Finally, in contrast to anorexigenic POMC neurons, a BNC2-specific knockout of LepR causes significant hyperphagia and obesity." (PMID 39478220, 2024). "Future investigations addressing isoform specificity, direct hormonal sensing, and human genetic relevance will be essential to evaluate BNC2 as a therapeutic target for obesity and related metabolic disorders." (PMID 42100744, 2026). "In these studies, we assessed the response to leptin 2 weeks after virus injection, which was before the time that the BNC2 LepR knockout mice developed obesity." (PMID 39478220, 2024). "To evaluate whether the impaired glucose tolerance and insulin action in BNC2 LepR knockout mice was a direct effect or secondary to their obesity, we modulated the activity of BNC2 neurons using chemogenetics." (PMID 39478220, 2024).
atherosclerosis (1 paper, 2025). A disease characterized by the build-up of fatty material and calcium deposition in the arterial wall resulting in partial or complete occlusion of the arterial lumen. "For novel atherosclerosis loci, 4 regions overlapped the most frequently across all stages of multi-trait analyses (nearest gene: BNC2, GPATCH2, INSR, JAZF1)." (PMID 40313769, 2025). "Of the 25 shared novel atherosclerosis loci with evidence of colocalization, 7 analyses strongly colocalized with PRPA ≥0.80 (nearest gene: BNC2, SCAI, TSC22D2, SRRM1, ABCB11, PRRX2)." (PMID 40313769, 2025).
brain arteriovenous malformations (1 paper, 2024). "Genome-wide association study of sporadic brain arteriovenous malformations showed Bnc2 intron SNP association with nominal p < 0.1." (PMID 39619203, 2024).
dwarfism (1 paper, 2023). "BNC2 expression is induced during cartilage differentiation in the developing arm and surviving BNC2−/− mice display dwarfism, leading to the suggestion that BNC2 may be required for the survival or development of chondrocytes." (PMID 37536977, 2023).
esophageal cancer (1 paper, 2015). A primary or metastatic malignant neoplasm involving the esophagus. "BNC2 has been identified as a tumor suppressor in esophageal cancer, based on single nucleotide polymorphism microarrays, and transfection and stable expression of BNC2 causes growth arrest of esophageal cancer cells." (PMID 25823933, 2015).
female infertility (1 paper, 2009). Diminished or absent ability of a female to achieve conception. "It will be interesting to discover if chromatophore loss and female infertility are linked through a common bnc2-dependent survival factor, as in Kit mutant mice." (PMID 19956727, 2009).
glioblastoma (1 paper, 2020). The most malignant astrocytic tumor (WHO grade IV). "Survival analysis revealed eight RBPs (PTRF, FNDC3B, SLC25A43, ZC3H12A, LRRFIP1, HSP90B1, HSPA5, and BNC2) are significantly associated with the survival of glioblastoma patients." (PMID 32272554, 2020).
Hepatic steatosis (1 paper, 2022). Steatosis is a term used to denote lipid accumulation within hepatocytes. "Hepatic steatosis and plasma transaminase activities were not significantly different between Bnc2+/+ and Bnc2+/− mice." (PMID 36088459, 2022).
idiopathic pulmonary fibrosis (1 paper, 2022). Idiopathic pulmonary fibrosis (IPF) is a nonneoplastic pulmonary disease that is characterized by the formation of scar tissue within the lungs in the absence of any known cause. "Of note, downregulation of matrisome gene expression upon BNC2 silencing was also found in LL-29 MF from human idiopathic pulmonary fibrosis further substantiating the conserved function of BNC2 in MFs." (PMID 36088459, 2022).
keratinocyte carcinoma (1 paper, 2024). A skin cancer arising from the keratin-producing cells of the epidermis. "The variant rs2026805 in BNC2 has been reported to be associated with keratinocyte carcinoma." (PMID 40040643, 2024).